SRPK1 (SRSF protein kinase 1)
Diseases named in the same sentence as SRPK1 in open-access papers (continued):
Sharing a sentence is not in itself a finding about the gene and the disease.
squamous cell lung carcinoma (2 papers, 2012 to 2015). A carcinoma arising from squamous bronchial epithelial cells. "Overexpression of SRPK1 and SRPK2 has also been found in lung tumors samples in percentages as high as 92% and 94% for lung adenocarcinoma and 72% and 68% for squamous cell lung carcinoma, respectively." (PMID 26273588, 2015). "Here, we demonstrate that not only SRSF1 but also SRSF2, SRPK1 and SRPK2 proteins are overexpressed in both adenocarcinoma and squamous cell lung carcinoma." (PMID 23071587, 2012).
amyotrophic lateral sclerosis (1 paper, 2024). Amyotrophic lateral sclerosis (ALS) is a neurodegenerative disease characterized by progressive muscular paralysis reflecting degeneration of motor neurons in the primary motor cortex, corticospinal tracts, brainstem and spinal cord. "Empirical evidence shows a strong link between SRPK1, and genes primarily implicated in AD, amyotrophic lateral sclerosis, and Parkinson's disease, which may explain the high coexistence of neurodegenerative diseases." (PMID 38376036, 2024).
autism (1 paper, 2016). Persistent deficits in social interaction and communication and interaction as well as a markedly restricted repertoire of activity and interest as well as repetitive patterns of behavior. "Previous studies have indicated that several differential alternative splicing genes (DAS), such as FXR1, C19orf2, GSN, and SRPK1, are associated with autism." (PMID 28000768, 2016).
cholangiocarcinoma (1 paper, 2025). A carcinoma that arises from the intrahepatic biliary tree (intrahepatic cholangiocarcinoma) or from the junction, or adjacent to the junction, of the right and left hepatic ducts (hilar cholangiocarcinoma). "Beyond VEGF, SRPK1 inhibition alters the splicing of MCL1/BIN1/BCL2 to produce pro-apoptotic isoforms in cholangiocarcinoma and causes stress-associated cell death in lymphoma." (PMID 41551143, 2025).
colon adenocarcinoma (1 paper, 2021). "Taken together, our data revealed an oncogenic role of SRPK1/2 signaling in colon adenocarcinoma cells." (PMID 33602301, 2021). "Additionally, the subcellular location of SRSF1, expression levels of SRPK1/2, as well as phosphorylation status of PP1α can all serve as independent prognostic predictors for the overall survival of colon adenocarcinoma." (PMID 33602301, 2021). "In colon adenocarcinoma cells, SRSF1 is hyperphosphorylated due to elevated SRPK1/2 and decreased PP1α activity, resulting in SRSF1 nucleus shuttling." (PMID 33602301, 2021).
dyslipidemia (1 paper, 2026).
endometrial cancer (1 paper, 2022). Primary or metastatic malignant neoplasm involving the endometrium (mucous membrane that lines the endometrial cavity). "SRPK1 was identified as having a likely role in primary endometrial cancer development." (PMID 35583632, 2022). "Pharmacological inhibition of SRPK1 with SPHINX31 was found to inhibit cell proliferation and induce apoptosis in endometrial cancer cells." (PMID 35583632, 2022). "For example, rather unexpectedly pharmacological inhibition of SRPK1 did not interfere with AKT signalling in endometrial cancer cells, with the authors suggesting a feedback loop may be present within the pathway." (PMID 35583632, 2022).
endothelial dysfunction (1 paper, 2022). In vascular diseases, endothelial dysfunction is a systemic pathological state of the endothelium (the inner lining of blood vessels) and can be broadly defined as an imbalance between vasodilating and vasoconstricting substances produced by (or acting on) the endothelium. "Based on previous research and current knowledge, the purpose of this study is to explore the role of SRPK1 in regulating endothelial homeostasis and the underlying mechanism of ICA II on PA-induced endothelial dysfunction in HUVECs." (PMID 35846993, 2022). "We found that the protective effect of ICA II against endothelial dysfunction induced by PA was significantly eliminated by inhibiting of SRPK1." (PMID 35846993, 2022). "The purpose of this study is to explore the role of SRPK1 in the biology of endothelial cells and the underlying mechanism of ICA II on palmitic acid (PA) induced endothelial dysfunction." (PMID 35846993, 2022). "The binding of Bio-ICA II and SRPK1 prompted us to examine whether ICA II alleviated PA-induced endothelial dysfunction by targeting SRPK1." (PMID 35846993, 2022). "On the other hand, ICA II could attenuate the PA-induced endothelial dysfunction and restore cell viability through the SRPK1-Akt-eNOS pathway." (PMID 35846993, 2022). "Taken together, these results demonstrated that ICA II could attenuate PA-induced endothelial dysfunction via SRPK1-Akt-eNOS pathway." (PMID 35846993, 2022). "We found that the expression level and phosphorylation level of the proteins associated with SRPK1-Akt-eNOS signaling pathway were significantly down-regulated in the presence of PA but greatly reversed using ICA II, indicating a promising therapeutic role of ICA II against endothelial dysfunction." (PMID 35846993, 2022). "In the present study, we demonstrated that ICA II protected against PA-induced endothelial dysfunction by activating SRPK1 via the direct interaction between ICA II and SRPK1." (PMID 35846993, 2022).
epithelial ovarian tumor (1 paper, 2012). "The experiments reported here show that SRPK1, a major regulator of the alternative splicing process, is elevated in more than 50% of epithelial ovarian tumor samples." (PMID 23236423, 2012).
gastric adenocarcinoma (1 paper, 2017). "Western blot results showed that SRPK1 expression was higher in gastric adenocarcinoma cells (SUN-1 and AGS cells) than normal gastric epithelial cells (GES-1 cells)." (PMID 28977917, 2017).
hypothyroidism (1 paper, 2015). Abnormally low levels of thyroid hormone. "The haplotype contains three genes (LHFPL5, SRPK1 and SLC26A8) with functions that are not explicitly obvious in the development of hypothyroidism." (PMID 26261983, 2015).
liver cancer (1 paper, 2023). An epithelial or non-epithelial malignant neoplasm that arises from the liver. "Together, DeepRescore2 provides a more comprehensive catalog of liver cancer-associated phosphosites, linking functional phosphosites and biological processes to liver cancer oncogenesis, and expanding the list of putative substrates of liver cancer-associated SRPK1 activity." (PMID 38154692, 2023).
lymph node metastasis (1 paper, 2022). "Moreover, the percentages of parametrial invasion and lymph node metastasis were significantly higher in high-SRPK1 group (P = 0.015 and P = 0.005, respectively)." (PMID 35192432, 2022).
lymphoma (1 paper, 2025). A malignant (clonal) proliferation of B- lymphocytes or T- lymphocytes which involves the lymph nodes, bone marrow and/or extranodal sites. "In lymphoma and myeloma, inhibiting SRPK1 induces ER stress and death through ATF4/CHOP activation and AKT suppression." (PMID 41551143, 2025).
metastatic melanoma (1 paper, 2022). A melanoma that has spread from its primary site to another anatomic site. "In summary, we have shown that in metastatic melanoma, high expression of SRPK1/2, especially SRPK2, contributes to the poor prognosis of patients." (PMID 36212152, 2022). "Taken together, these findings suggest different functional roles for SRPK1/2 in metastatic melanoma and highlight the relevance of pursuing selective pharmacological inhibitors of SRPK2." (PMID 36212152, 2022).
mucinous tumors (1 paper, 2021). "Similarly, SRSF protein kinase 1 (SRPK1) was mutated in 10.45% of mucinous tumors compared with only 3.23% of non-mucinous tumors." (PMID 33808549, 2021).
myelodysplastic syndrome (1 paper, 2025). A clonal hematopoietic disorder characterized by dysplasia and ineffective hematopoiesis in one or more of the hematopoietic cell lines. "In NDGs, splicing disruptions were detected in SRPK1, a splicing kinase involved in neutrophil development and linked to myelodysplastic syndromes." (PMID 41279038, 2025).
non-Hodgkin lymphoma (1 paper, 2022). Distinct from Hodgkin lymphoma both morphologically and biologically, non-Hodgkin lymphoma (NHL) is characterized by the absence of Reed-Sternberg cells, can occur at any age, and usually presents as a localized or generalized lymphadenopathy associated with fever and weight loss. "In the present study, we initially evaluated the clinical significance of SRPK1 in extranodal natural killer/T-cell lymphoma (ENKTL), a very aggressive subtype of non-Hodgkin lymphoma." (PMID 36303126, 2022).
nonseminomatous germ cell tumors (1 paper, 2022). "SRPK1 was later confirmed to be a cisplatin sensitivity gene in nonseminomatous germ cell tumors." (PMID 36303126, 2022).
osteosarcoma (1 paper, 2022). A usually aggressive malignant bone-forming mesenchymal neoplasm, predominantly affecting adolescents and young adults. "Ultimately, this data demonstrated that miR-659-3p negatively regulates SRPK1 expression and plays a role in osteosarcoma cells proliferation, migration, and invasion." (PMID 36038837, 2022). "We revealed that expression of miR-659-3p was significantly downregulated in osteosarcoma compared with normal bone cells and was inversely correlated with serine-arginine protein kinase 1 (SRPK1) expression." (PMID 36038837, 2022). "Our current data indicated that inhibiting SRPK1 by miR-659-3p increased osteosarcoma cells G1/G0 phase arrest." (PMID 36038837, 2022). "To further prove that miR-659-3p regulates osteosarcoma cells proliferation, migration, and invasion through SRPK1, we utilized the SRPK1 gain-of-function strategy." (PMID 36038837, 2022). "In vitro studies revealed that gain of miR-659-3p function inhibited osteosarcoma cells growth, migration, and invasion by down-regulating SRPK1 expression." (PMID 36038837, 2022). "This study demonstrated that miR-659-3p is a potential therapeutic method and SRPK1 is a potential therapeutic target for osteosarcoma treatment." (PMID 36038837, 2022). "We found that the miR-659-3p expression exhibited a reverse correlation with the expression of SRPK1 in osteosarcoma cell lines." (PMID 36038837, 2022). "Overexpression of SRPK1 significantly increased HOS osteosarcoma cells proliferation (compare green line with blue line) and rescued miR-659-3p inhibition of HOS cells proliferation (compare purple line with red line)." (PMID 36038837, 2022). "The mRNA expression of SRPK1 was significantly upregulated in the osteosarcoma cell lines compared to normal bone cell lines." (PMID 36038837, 2022). "In this study, we identified miR-659-3p as a negative regulator of SRPK1 gene in osteosarcoma cells." (PMID 36038837, 2022). "By using an in vivo mouse model, we demonstrated that miR-659-3p inhibits osteosarcoma tumor progression and lung metastasis by inhibiting SRPK1 expression and potentially downstream cell proliferation, and epithelial-to-mesenchymal transition genes." (PMID 36038837, 2022). "Taken together, this study revealed that miR-659-3p negatively regulates SRPK1 expression in osteosarcoma cells, inhibits osteosarcoma cells growth, migration, and invasion in vitro." (PMID 36038837, 2022). "In this study, we found a novel miR-659-3p-SRPK1 axis that regulates osteosarcoma cells growth, migration, invasion in vitro, and tumor progression and metastasis in vivo." (PMID 36038837, 2022). "To further elucidate the role of SRPK1 in miR-659-3p inhibition of osteosarcoma cells invasion, we used the same groups of cells as above and performed a transwell cell invasion assay." (PMID 36038837, 2022). "We proved that miR-659-3p targets 3’ UTR of SRPK1 and negatively regulates SRPK1 expression in osteosarcoma cells via luciferase assay." (PMID 36038837, 2022). "We evaluated miR-659-3p and SRPK1 function in osteosarcoma cell proliferation, migration, and cell cycle progression in vitro by using gain- and loss-of-function strategies." (PMID 36038837, 2022). "HOS osteosarcoma cells were co-transfected with pCDNA3.1 expression vector containing human SRPK1 cDNA sequence (SRPK1/pCDNA) and miR-659-3p mimic." (PMID 36038837, 2022). "For the first time, we reported that miR-659–39 inhibits osteosarcoma cells growth in vitro and inhibits osteosarcoma tumor progression and metastasis in vivo by targeting SRPK1 gene expression." (PMID 36038837, 2022). "Cell cycle profile analysis revealed that miR-659-3p inhibited osteosarcoma cells’ G1/G0 phase exit by down-regulating SRPK1 expression." (PMID 36038837, 2022). "In contrast, knocking down SRPK1 expression by miR-659-3p mimics decreased osteosarcoma cells migration (Mimic + vector)." (PMID 36038837, 2022).
osteosarcoma (continued). "The findings that miR-659-3p targeted SRPK1 3’UTR, negatively regulated SRPK1 expression, and regulated osteosarcoma cell proliferation lead us to further explore the hypothesis that miR-659-3p affects osteosarcoma cell cycle progression through SRPK1." (PMID 36038837, 2022). "In this study we aimed to elucidate the role of miR-659-3p and SRPK1 in osteosarcoma." (PMID 36038837, 2022). "In the wound healing assay, the gap sizes of SRPK1 overexpressed cells were significantly smaller than the controls (compare green line with blue line, and purple line with red line), which indicated that overexpression of SRPK1 increased osteosarcoma cells migration." (PMID 36038837, 2022). "Moreover, SRPK1 overexpression increased the capability of osteosarcoma cell invasion and rescued the inhibitory effect of miR-659-3p." (PMID 36038837, 2022). "The present study hinted at least two different mechanisms of SRPK1 in osteosarcoma." (PMID 36038837, 2022). "Thus, we performed preliminary screening of 5 novel miRNAs potentially targeting SRPK1 in osteosarcoma cell lines." (PMID 36038837, 2022). "However, SRPK1 overexpression mitigated inhibition of osteosarcoma cells migration by miR-659-3p (compare purple line with red line)." (PMID 36038837, 2022). "Here we first asked the question of whether miR-659-3p inhibits osteosarcoma cells proliferation in vitro by negatively regulating SRPK1 expression." (PMID 36038837, 2022). "The finding that miR-659-3p mimic inhibits SRPK1 expression and inhibits osteosarcoma cells proliferation and migration, leads us to further hypothesis that inhibiting miR-659-3p in osteosarcoma cells will promote cell proliferation and migration." (PMID 36038837, 2022). "First, SRPK1 plays a role in the osteosarcoma cell cycle regulation." (PMID 36038837, 2022). "We thus hypothesized that the mechanism of miR-659-3p inhibiting osteosarcoma cell growth at least in part is that miR-659-3p down regulates SRPK1 expression and promotes osteosarcoma cell apoptosis." (PMID 36038837, 2022). "This study provided evidence not only that SRPK1 could be used as a therapeutic target for osteosarcoma treatment, but also that miR-659-3p could potentially be used as a tool for targeting SRPK1 in osteosarcoma treatment." (PMID 36038837, 2022). "Taken together, elucidating whether SRPK1 plays a role in osteosarcoma progression and metastasis may provide novel osteosarcoma novel treatment target, and identification of novel miRNAs target SRPK1 in osteosarcoma may also provide a new therapeutic method for osteosarcoma treatment." (PMID 36038837, 2022). "Thus, we further investigated whether SRPK1 overexpression can rescue the effect of miR-659-3p on osteosarcoma cell G1/G0 phase exit." (PMID 36038837, 2022). "In this study, we revealed that SRPK1 may regulate cell proliferation molecules such as PCNA and Ki67 to play a critical role in osteosarcoma cell proliferation and tumor progression." (PMID 36038837, 2022). "In order to identify the miRNAs that target SRPK1, we analyzed differentially expressed microRNAs in the existing data set from NCBI Gene Expression Omnibus GSE28423, which was performed on 19 human osteosarcoma cell lines with 4 normal bone cell lines as control." (PMID 36038837, 2022). "SRPK1 plays a role in several cancers, although whether SRPK1 plays any role in osteosarcoma has not been established." (PMID 36038837, 2022). "However, whether SRPK1 plays any role in osteosarcoma is not clear." (PMID 36038837, 2022).
ovarian tumors (1 paper, 2012). "Our results using immunohistochemical staining on a limited number of samples provided a strong hint that SRPK1 is overexpressed in ovarian tumors, compared with normal ovarian epithelium." (PMID 23236423, 2012). "First, we found that elevated SRPK1 protein level was present in approximately 55% of ovarian tumor samples as compared with non-neoplastic ovarian tissue samples." (PMID 23236423, 2012).
parasitemia (1 paper, 2017). "For three other genes, Tb927.2.2430 (Other/CK2A2), Tb927.7.960 (CMGC/SRPK1) and Tb927.10.14300 (STE11/MRK1), the loss of fitness after in vivo RNAi was even more pronounced, since a decrease in parasitemia or clearance was seen before 96 h." (PMID 28733613, 2017).
preeclampsia (1 paper, 2022). Preeclampsia is a hypertensive disorder of pregnancy that is characterized by new-onset hypertension with proteinuria presenting after 20 weeks of gestation, and depending on mild or severe forms may initially present with severe headache, visual disturbances, and hyperreflexia. "A regression model using five RNAs selected for ‘pregnancy hypertension’ (preeclampsia and gestational hypertension) yielded good predictive power with an AUC of 0.86, and like the present study, their proposed RNA panel included NAMPT (the remaining markers were MMP8, SRPK1, S100A9, and S100A8)." (PMID 35741140, 2022).
prostatic intraepithelial neoplasia (1 paper, 2022). "SRPK1 expression is elevated in both malignant prostate cancer and interestingly prostatic intraepithelial neoplasia (PIN)." (PMID 35583632, 2022).
Sepsis (1 paper, 2024). Sepsis is defined as life-threatening organ dysfunction caused by a dysregulated host response to infection. "For instance, serine-arginine protein kinase 1 (SRPK1) can inhibit sepsis-induced acute lung injury (ALI) by modulating the PI3K/AKT/ forkhead box O 3/NLRP3 pathway." (PMID 38716051, 2024). "SRPK1 overexpression can promote cell proliferation, inhibit apoptosis in primary human pulmonary microvascular endothelial cells, and alleviate sepsis-induced ALI in vivo through forkhead box O 3-mediated transcriptional inactivation of NLRP3 and inhibition of NLRP3 mRNA and protein expression." (PMID 38716051, 2024). "However, SRPK1 levels are decreased in patients with sepsis-induced ALI." (PMID 38716051, 2024).
sinonasal undifferentiated carcinoma (1 paper, 2021). A rare, highly aggressive carcinoma that arises from the sinonasal tract. "This is the first study to date to suggest a role of SRPK-1 in sinonasal undifferentiated carcinoma." (PMID 34051734, 2021).
T-cell acute lymphoblastic leukaemia (1 paper, 2022). "SRPK1 expression is associated with PI3K/AKT signalling in T-cell acute lymphoblastic leukaemia (T-ALL) cell lines." (PMID 35583632, 2022).
viral-infection (1 paper, 2016). "Some viral-infection-related genes, such as Il1a and Srpk1, exhibited gains of stop codons, which may correlate with the ability of the AHR to serve as a pathogen carrier." (PMID 27172215, 2016).